GBE1 (1,4-alpha-glucan branching enzyme 1)
Diseases named in the same sentence as GBE1 in open-access papers (continued):
Sharing a sentence is not in itself a finding about the gene and the disease.
tumor (22 papers, 2011 to 2025). "The result of the CIBERSORT algorithm revealed that GBE1 expression was significantly correlated with infiltration of CD163+ tumor-associated macrophages." (PMID 35155189, 2021). "The result revealed that GBE1 was strongly positively related to the CD163+ tumor-associated macrophage infiltration, which was consistent with the results of CIBERSORT algorithm, TIMER database, and TCGA cohort." (PMID 35155189, 2021). "Furthermore, the results of WB from U251 cells showed that changes in proteins related to tumor biological behaviors caused by single GBE1 knockdown were also reversed after FBP1 knockdown, which was paralleled to the alterations in tumor phenotypes." (PMID 36900384, 2023). "Moreover, GBE1 was positively correlated with infiltrating levels of CD163+ tumor-associated macrophages in LUAD." (PMID 35155189, 2021). "High expression of GBE1 may promote high infiltration level of CD163+ tumor-associated macrophages in LUAD." (PMID 35155189, 2021). "Our results implied that expression of GBE1 may be related with CD163+ tumor-associated macrophage infiltration in LUAD." (PMID 35155189, 2021). "Next, we tested whether blockade of GBE1 combined with anti-PD-L1 antibody increases anti-tumor immunity to cause sustained inhibition of tumor growth in vivo." (PMID 31221150, 2019). "This study established a link between GBE1 expression and metabolic alterations that drive tumor progression, illustrating how specific metabolic enzymes mediate hypoxia-induced changes in tumor behavior." (PMID 40322886, 2025). "Recently, GBE1 was reported as an oncogene in the cell growth, migration, stemness, glycolysis and anti-tumor immunity of lung adenocarcinoma (LUAD)." (PMID 38961325, 2024). "Mechanically, we revealed that WTAP and IGF2BP3 regulated GBE1 expression via m6A modification and also demonstrated that GBE1 facilitates PC cell proliferation, stemness-like properties and tumor growth." (PMID 38961325, 2024). "For instance, fructose-1,6-bisphosphatase (FBP1) inhibits tumor progression in LUAD, while hypoxia-mediated glycogen amylase (GBE1) can promote tumor progression." (PMID 38074028, 2023). "The glycogen branching enzyme (GBE1) is thought to be a major regulator of cancer microenvironment; the tumor microenvironment is a complex of cells and factors that enables tumor growth and development." (PMID 36268271, 2022). "In conclusion, the expression of GBE1 is associated with the prognosis and CD163+ tumor-associated macrophage infiltration in LUAD, suggesting that it has potential to be prognostic and immunological biomarkers in LUAD." (PMID 35155189, 2021). "We further used TMA-based IHC to confirm the positive relationship between GBE1 expression level and CD163+ tumor-associated macrophage infiltration." (PMID 35155189, 2021). "The expression level of GBE1 was associated with prognosis and CD163+ tumor-associated macrophage infiltration in LUAD, suggesting its potential utility as a prognostic biomarker and immune-related therapeutic target for LUAD patients." (PMID 35155189, 2021). "Taken together, the results indicate that hypoxia supports the Warburg effect to promote tumor progression via GBE1 induction and that GBE1-mediated FBP1 suppression via FBP1 promoter methylation enhances HIF1α levels through NF-κB signaling in LUAD tissues." (PMID 32439898, 2020). "Herein, we demonstrate that GBE1 is an important transcriptional target of HIF1α signaling and can promote tumor progression by regulating the methylation of FBP1 via the NF-κB signaling pathway in LUAD cells." (PMID 32439898, 2020). "Herein, the effect of GBE1 on tumor progression via changes in metabolic signaling under hypoxia in vitro and in vivo was evaluated, and GBE1-related genes from human specimens and data sets were analyzed." (PMID 32439898, 2020).
tumor (continued). "This is the first study to show that GBE1 is transcriptionally regulated by HIF1α and that GBE1, a critical downstream effector of HIF1α, affects tumor progression." (PMID 32439898, 2020). "Next, we evaluated the relationship between GBE1 expression and clinical pathological parameters in the TCGA data set and found that the expression of GBE1 in the tumor tissues of late-stage LUAD patients was significantly increased." (PMID 32439898, 2020). "LUAD patients with high levels of GBE1 in tumor tissues had a worse OS, suggesting that GBE1 is an independent prognostic marker of OS." (PMID 32439898, 2020). "Similar to GBE1, HIF1α is increased in late-stage tumors and is closely correlated with tumor progression." (PMID 32439898, 2020). "GBE1-knockdown A549 cells showed impaired cell proliferation, clone formation, cell migration and invasion, angiogenesis, tumor growth, and metastasis." (PMID 32439898, 2020). "Collectively, GBE1 is a critical determinant of tumor progression and represents a potential therapeutic target for tumor treatment." (PMID 32439898, 2020). "This study explored the mechanistic details of glycogen metabolism by GBE1 in tumor cells for its critical role in tumor growth and enhancing malignancy under hypoxia." (PMID 31221150, 2019). "PD-L1 protein expression was elevated in low-GBE1 expression areas of the tumor tissues and vice versa, as determined by immunofluorescence assay." (PMID 31221150, 2019). "Lastly, blockade of GBE1 signaling combined with anti-PD-L1 antibody significantly inhibited tumor growth in vivo." (PMID 31221150, 2019). "Accordingly, we propose that GBE1 reduces the recruitment of CD8+ T cells into the tumor microenvironment by inactivating CCL5 and CXCL10, thus contributing to the immune escape in LUAD." (PMID 31221150, 2019). "Reduced expression of GBE1 not only affects glucose metabolism pathways but also has a broader effect on the tumor microenvironment, ultimately resulting in reduced LUAD cell growth in vitro and in vivo." (PMID 31221150, 2019). "Moreover, subcutaneous mouse model and orthotopic mouse model further demonstrated the role of GBE1 in facilitating PC tumor growth in vivo." (PMID 38961325, 2024). "Moreover, decreased expression of c-Myc and Ki67 in GBE1 knockdown group was revealed in the tumor tissues of pancreatic subcutaneous and orthotopic xenograft model, which was consistent with our above findings." (PMID 38961325, 2024). "An upregulation of c-Myc level was observed in the tumor tissues upon GBE1 overexpression." (PMID 38961325, 2024). "Furthermore, the intracranial tumor formation assay also validated the inhibitory effect of GBE1 knockdown in a complex tumor microenvironment." (PMID 36900384, 2023). "Furthermore, GBE1 knockdown suppressed xenograft tumor formation in vivo and conferred a significant survival benefit." (PMID 36900384, 2023). "Therefore, our study shed light on the role of GBE1 in tumor progression and its potential to be a prognostic biomarker." (PMID 35155189, 2021). "Our study may provide new insights into the important roles of GBE1 in LUAD and reveal a potential relationship between GBE1 and tumor microenvironment." (PMID 35155189, 2021). "Moreover, we explored the correlation between GBE1 expression and the tumor-infiltrating immune cells in different tumor microenvironments via the CIBERSORT algorithm and TIMER database." (PMID 35155189, 2021). "Furthermore, we verified the relationship between GBE1 expression and CD163+ tumor-associated macrophages via IHC staining." (PMID 35155189, 2021). "However, the hypoxia-mediated molecular mechanism of tumor progression via GBE1 is not fully understood." (PMID 32439898, 2020). "Moreover, GBE1 protein levels and HIF1α expression were obviously higher in tumor tissues than they were in the paired peritumor tissues." (PMID 32439898, 2020).
tumor (continued). "We next investigated whether GBE1 expression had prognostic value by using tumor tissues from a clinically annotated cohort of 75 LUAD patients." (PMID 32439898, 2020). "The results showed that GBE1 promoted tumor progression under hypoxia in vitro." (PMID 32439898, 2020). "Notably, blocking GBE1 resulted in a marked reduction in tumor growth, as indicated by tumor volume and weight, compared with the volume and weight of the control." (PMID 32439898, 2020). "In the present study, we showed that blockade of GBE1 could promote anti-tumor immunity via activation of the IFN-I pathway through STING signaling." (PMID 31221150, 2019). "We further demonstrate that depletion of GBE1 can upregulate CCL5 and CXCL10 expression through STING signaling to activate IFN-I pathway, potentiate T cell infiltration, and cause induced expression of PD-L1 on tumor cells simultaneously." (PMID 31221150, 2019). "In this setting, anti-PD-L1 antibody combined with GBE1 blockade remarkably delayed tumor growth." (PMID 31221150, 2019). "Our experimental results confirm the hypothesis that GBE1 inhibits T cell infiltration in the tumor microenvironment and increases PD-L1 expression in tumor cells." (PMID 31221150, 2019). "Here, we show a definitive role of GBE1 in the infiltration of T lymphocytes into tumor sites." (PMID 31221150, 2019). "Therefore, GBE1 may be a promising target for cancer immunotherapy to achieve tumor regression in LUAD." (PMID 31221150, 2019). "Studies have revealed that GBE1 enhanced LUAD cell growth, migration, stemness, glycolysis and anti-tumor immunity, indicating GBE1 as a therapeutic target for LUAD." (PMID 38961325, 2024). "On the one hand, GBE1 is highly expressed in acute myeloid leukemia (AML) and maintains abnormal tumor cell proliferation by inhibiting AMPK activity." (PMID 36900384, 2023). "We then investigated the relationships between GBE1 and infiltration of immune cells in LUAD by utilizing the CIBERSORT algorithm and Tumor Immune Estimation Resource (TIMER) database." (PMID 35155189, 2021). "In summary, this study provides novel insight showing that hypoxia-induced HIF1α mediates GBE1 upregulation, which suppresses FBP1 expression by promoter methylation via NF-κB signaling in the tumor microenvironment of LUAD." (PMID 32439898, 2020). "We also found that GBE1 expression was progressively increased in LUAD tissues according to the TNM staging system based on tumor size, N staging and tumor stage, with a similar but weak reactivity observed in the paired normal lung tissues." (PMID 32439898, 2020). "To investigate this further, we performed mutation analysis in 1781T of protein coding regions and intron/exon splice junction sites of the top 3p12-pcen tumour suppressor gene candidates, ROBO1, GBE1 and VGLL3." (PMID 22163003, 2011). "GBE1 knockdown can promote the secretion of CCL5 and CXCL10, and the recruitment of CD8+ T lymphocytes into the tumor microenvironment, suggesting that GBE1 may be an important target to inhibit the progression of LUAD tumor through immunotherapy." (PMID 37187527, 2023). "However, the roles of GBE1 in LUAD progression and tumor microenvironment are still needed to further explore." (PMID 35155189, 2021). "In the present study, we identified a novel function for FBP1 in inhibiting tumor progression and explored whether the abnormal regulation of FBP1 is involved in GBE1-induced cellular transformation and carcinogenesis." (PMID 32439898, 2020). "Collectively, GBE1 prevents CCL5 and CXCL10 secretion in LUAD cells, which may further affect the recruitment of T lymphocytes into the tumor microenvironment." (PMID 31221150, 2019). "Six genes, RPL13A, KLF6, LOC100129599, GBE1, PDGFA, and UHRF1 were altered in lymph node metastases of both cell lines relative the primary tumor, suggesting they may represent changes important for metastatic growth in lymph nodes." (PMID 23118918, 2012).
tumor (continued). "Additionally, GBE1 blockade could promote the secretion of CCL5 and CXCL10 to recruit CD8+ T lymphocytes to the tumor microenvironment via the IFN-I/STING signaling pathway, accompanied by upregulation of PD-L1 in LUAD cells." (PMID 35155189, 2021). "Collectively, these results indicate that GBE1 blockade induces IFN-I production via STING signaling pathway, accompanied by upregulation of PD-L1 in LUAD cells, which further enhances the secretion of CCL5 and CXCL10 to recruit CD8+ T lymphocytes in the tumor microenvironment." (PMID 31221150, 2019). "Notably, FAM120A and GBE1 were significantly expressed in multiple cell types, suggesting their roles in CRC cell proliferation and providing new insights into their functions in tissue regeneration, inflammatory response, and tumor microenvironment regulation." (PMID 41049004, 2025). "This phenomenon may possibly be due to GBE1 knockdown, which suppressed tumor development by non-immune pathways leading to the upregulation of PD-L1 expression on A549 cells, and simultaneously reduced tumor growth at a rate similar to that seen in the group that received anti-PD-L1 alone." (PMID 31221150, 2019). "Additionally, in LUAD tumor tissues, a negative link between PD-L1 and GBE1 was observed." (PMID 31221150, 2019).
cancer (11 papers, 2015 to 2024). A tumor composed of atypical neoplastic, often pleomorphic cells that invade other tissues. "In addition, cancer genomics data indicate that elevated levels of the glycogenic enzyme GBE1 are associated with poor survival in AML." (PMID 29312568, 2017). "Recent studies have found that glycogen branching enzyme 1 (GBE1) is involved in cancer progression." (PMID 36900384, 2023). "GBE1 knockdown is shown to be correlated with increased and enhanced immune response, thus inhibiting, and limiting the growth of the cancer cells." (PMID 36268271, 2022). "Currently, little study about GBE1 has been reported in human cancers except LUAD." (PMID 38961325, 2024). "Furthermore, data based on the RNA-seq analysis revealed that the knockdown of GBE1 in A549 cells significantly upregulated or downregulated the expression of cancer immune-related cytokines and chemokines." (PMID 31221150, 2019). "Additionally, it will be of interest to explore whether GBE1 involved in any other malignant behaviors of PC, since GBE1 are critical for glycogen accumulation and involved in anti-cancer immunity." (PMID 38961325, 2024). "Moreover, this research showed that GBE1 expression was necessary for cancer progression." (PMID 32439898, 2020). "However, the importance and regulation of GBE1 in cancer biology and clinical oncology are unclear." (PMID 32439898, 2020). "Additionally, the function of a few other genes, such as GBE1 and CADM2 in 3p12.1, has not been intensively studied in cancers and thus deserve further investigation." (PMID 26386145, 2015).
metabolic disease (6 papers, 2015 to 2025). A congenital disorder (due to inherited enzyme abnormality) or acquired (due to failure of a metabolically important organ) disorder resulting from an abnormal metabolic process. "This is a rare hereditary metabolic disease caused by mutations of the GBE1 glycogen-branching enzyme." (PMID 34940418, 2021). "GSD IV is a rare autosomal recessive metabolic disorder caused by GBE1 mutations and accounts for <1% of GSDs." (PMID 33344388, 2020). "In the current study, using WES technology, we have identified four different genetic variants in BTD, ASL, GBE1 and AGL in four Saudi families as an underlying cause of metabolic disorders." (PMID 38592052, 2024).
adenocarcinoma (2 papers, 2021 to 2022). A common cancer characterized by the presence of malignant glandular cells. "What's more, glycogen branching enzyme (GBE1) was also involved in the immune dysregulation in adenocarcinoma NSCLC." (PMID 33230935, 2021).
neuromuscular disease (2 papers, 2015). "Mutations were found in eight previously known neuromuscular disease genes (CHRND, CHNRG, ECEL1, GBE1, MTM1, MYH3, NEB and RYR1) and four novel neuromuscular disease genes (GPR126, KLHL40, KLHL41 and SPEG)." (PMID 26933539, 2015). "Within this cohort, mutations were found in eight previously known neuromuscular disease genes (CHRND, CHNRG, ECEL1, GBE1, MTM1, MYH3, NEB and RYR1) and four novel neuromuscular disease genes were identified and have been published as separate reports (GPR126, KLHL40, KLHL41 and SPEG)." (PMID 26578207, 2015).
inherited metabolic disorder (1 paper, 2024). "Moreover, functional enrichment analysis by STRING showed that BTD, ASL, GBE1 and AGL are among 726 genes co-expressed during inherited metabolic disorder." (PMID 38592052, 2024).
GBE1 also shares sentences with these, for which no sentence is quoted: Obesity (7 papers); diabetes (3); acute myelocytic leukemia (2); breast cancer (2); Cognitive impairment (2); hydrops (2); mitochondrial disease (2); mucopolysaccharidosis VII (2); Neurogenic bladder (2); neurological disease (2); squamous carcinoma (2); Adult onset (1); Alzheimer disease (1); Anderson disease (1); Anxiety (1); atherosclerosis (1); autonomic dysfunction (1); axonal neuropathy (1); bladder cancer (1); cognitive decline (1); congenital myasthenic syndrome (1); Danon disease (1); depression (1); dysautonomia (1); dyslexia (1); enteropathy (1); epilepsy (1); erectile dysfunction (1); erythropoietic porphyria (1); Fabry disease (1).
A further 27 diseases each share a sentence with GBE1 in 1 paper.